CCND1 (cyclin D1)
Diseases named in the same sentence as CCND1 in open-access papers (continued):
Sharing a sentence is not in itself a finding about the gene and the disease.
breast tumors (continued). "Due to the significant reduction of the cyclin D1, it can be concluded that limonene may lead to the arrest of the cell cycle and suppress the expansion of cells in breast tumors." (PMID 40612872, 2025). "The histologic analysis further revealed that the degree of CCND1 staining was lower (CCND1‐negative) in breast tumor tissues with high ZC3H12D staining (ZC3H12D‐positive), but greater CCND1 staining (CCND1‐positive) was observed in breast tumor tissues with greater DDX5 staining (DDX5‐positive)." (PMID 41263459, 2025). "As expected, CCND1 is also highly expressed in breast tumor samples." (PMID 40233410, 2025). "Cyclin D1, a key cell regulator predominantly located in the nucleus when inactive, is phosphorylated at residue T286 by IKKα leading to cyclin D1 dysregulation and wide subcellular distribution, which drives progression of lung and breast tumours." (PMID 40763800, 2025). "The high expression of the CCND1 mRNA in breast tumor cells led us to look for potential RBPs that could compensate for the degradation by ZC3H12D." (PMID 41263459, 2025). "Because cells in breast tumors have also been reported to be subject to increased compressive stress, we wondered whether cyclin D1 may be adaptive in the context of a compressive solid tumor." (PMID 38478555, 2024). "For example, aberrant STAT3 signaling promotes breast tumor progression through deregulation of the expression of downstream target genes, which control proliferation (Bcl-2, Bcl-xL, survivin, cyclin D1, c-Myc, and Mcl-1), angiogenesis (Hif1α and VEGF), and EMT (vimentin, Twist, MMP-9, and MMP-7)." (PMID 36446524, 2023). "The region 11q13 is a gene-rich region found amplified in 15% of all primary breast tumors, and hosts genes known as potential contributors to positive selection for cell proliferation and survival by previous studies, among which the oncogene CCND1." (PMID 36010918, 2022). "The variety of distinct genetic mechanisms giving rise to therapy resistance may, in part, reflect the intrinsic genomic instability of cyclin D1 overexpressing breast tumors." (PMID 36358806, 2022). "Palbociclib-responsive breast tumors are ER+, Rb+ with cyclin D1 overexpression." (PMID 36358806, 2022). "Also, compared to controls, only anti-CD40-CD40L-Cyclin D1 vaccination of human CD40 mice reduced implanted EO771.LMB breast tumor cell growth." (PMID 35095862, 2021). "In both cohorts, PLK1 expression was higher in the group of CCND1-amplified breast tumours." (PMID 32792481, 2020). "In order to determine whether stromal cyclin D1 induced autophagy in the breast tumor we assessed known markers." (PMID 29137220, 2017). "Accordingly, the immunohistochemistry detection indicated that resveratrol administration could significantly reduce the expression of β-catenin and cyclin D1 in xenograft breast tumors in vivo." (PMID 25068516, 2014). "For example, increased cyclin D1 and decreased cdk6 levels are seen in many human breast tumors." (PMID 24848372, 2014). "In the present study, CCND1 gene amplification did not appear to be confirmed as a predictive biomarker for adjuvant tamoxifen in high-risk breast tumors in pre-menopausal patients in the MA.12 study." (PMID 24367492, 2013). "While these studies addressed the importance of cyclin D1 on breast tumor initiation, its contribution to the development and progression of established tumors remains unclear." (PMID 23786849, 2013). "Moreover, PHD1 inactivation resulted in lower levels of Cyclin D1 and impaired breast tumour formation." (PMID 24195777, 2013). "Thus, as expected, RSF1 and CCND1 genes were frequently co-amplified in this cohort of breast tumors." (PMID 24367492, 2013). "Also, the combination was more effective in down-regulating the expression of NF-kB-regulated gene products (cyclin D1 and Bcl-2) in breast tumor tissues." (PMID 23284617, 2012).
breast tumors (continued). "In addition, the combination treatment induced an apoptotic effect evidenced by TUNEL staining and significantly decreased the expression of cyclin D1 and Bcl-2 in breast tumor tissues." (PMID 23284617, 2012). "In human breast tumors, activation of cyclin D1 is a common event." (PMID 20174572, 2010). "In the literature, Cyclin D1 amplification in primary breast tumours ranged between 10 and 23%." (PMID 17262082, 2007). "Amplification of CCND1 was found in 19.6% which is close to what is usually found in breast tumors." (PMID 17040570, 2006). "In summary, our data suggest that the MMTV-cortactin transgenic mice neither develop breast tumors nor accelerate MMTV-cyclin D1-induced mammary tumorigenesis on top of the causal MG tumors that arose in the aged FVB/N mice." (PMID 16536875, 2006). "Abrogation of Rb pathway function is frequent in breast tumors by loss of expression of Rb or altered expression of inhibitors of Rb activity (e.g. loss/silencing of CDKN2A (p16) and amplification and/or over expression of CCND1, CDK4, CDK6)." (PMID 16620391, 2006). "The aim of this study was to assess the prognostic significance of CCND1 status at both the RNA level (to identify overexpression) and the DNA level (to identify gene amplification) in 134 unilateral invasive primary breast tumours with a known long-term outcome." (PMID 11870541, 2002). "Among the 134 breast tumour RNA samples tested, 44 (32.8%) showed CCND1 overexpression." (PMID 11870541, 2002). "Overexpression of cyclin D1 appeared to be associated with oestrogen receptor-positive breast tumours, but not with any other clinicopathological parameter tested." (PMID 8611372, 1996). "Notably, DDX5 and ZC3H12D could positively and negatively regulate the expression of CCND1, respectively, in human breast tumors." (PMID 41263459, 2025). "Thus, cyclin D1 may play a broader role in regulating the activity and self-renewal properties of various progenitor cells in various breast tumors of different molecular subtypes." (PMID 33649296, 2021). "In addition, cyclin D1-deficient mice do not grow breast tumors when induced by the oncogenes Ras and Neu, further supporting cyclin D1 as a key driver in certain breast tumors." (PMID 20525379, 2010). "Finally, cyclin D1 is frequently overexpressed in ductal carcinoma in situ, and also in some benign breast diseases, pointing to a role in the earliest stages of breast tumour development." (PMID 11870541, 2002). "To define the effects of DDX5 on ZC3H12D‐induced CCND1 mRNA degradation, we overexpressed DDX5 in ZC3H12D‐overexpressing breast tumor cells and then performed an mRNA stability assay." (PMID 41263459, 2025). "Although ZC3H12D expression was already lower in breast tumor cells, further knockdown of ZC3H12D significantly increased the mRNA expression of cell cycle‐promoting genes, including CCND1." (PMID 41263459, 2025). "Patient’s breast tumour and bone metastasis-derived PDX show amplification of FGFR1, MYC, CCNE2, CCND1 and AURKA." (PMID 32792481, 2020). "Common oncogenic drivers such as CCND1 and FGFR1 or FGFR2 were amplified in the primary breast tumours and can be considered early events in these patients’ tumours." (PMID 32792481, 2020). "The CNA profile of the primary breast tumour, the bone metastasis and the PDX, were highly similar with focal amplification of FGFR1, FGFR2 and CCND1 and CN gains of CCNE2." (PMID 32792481, 2020). "Human breast tumors also have lower levels of LPP1 and higher levels of cJUN, cFOS, MMP-1, -7, -8, -9, -12, -13, cyclin D1, and cyclin D3 relative to normal breast tissue." (PMID 31534541, 2019). "These human breast tumors had higher content of cFOS, cJUN, FRA1, cyclin D1 and cyclin D3 compared to normal breast tissue." (PMID 31534541, 2019). "We measured the extent to which the transcriptomes of breast tumors with amplifications of ERBB2, MYC or CCND1 oncogenes are due to the accompanying onco-passenger CNVs." (PMID 29069713, 2017).
breast tumors (continued). "Breast tumors from HFD group exhibited elevated expression of MTA1, β-catenin and cyclin D1 which was efficiently abrogated by HNK treatment." (PMID 26036628, 2015). "Recent research showed that ZNF703 is amplified in approximately 15% of breast tumors, which is only less than HER2 and cyclin D1 (CCND1), especially in Luminal B molecular subtypes; thus, more attention has been focused on ZNF703." (PMID 26063961, 2015). "For instance, 30–40 % of breast tumors with amplification of the FGFR1-containing chromosomal region 8p12, were concurrently presented with CCND1 (Cyclin D1) gene amplification at the 11q13 locus." (PMID 23900974, 2013). "To investigate the relationship between CCND1 and ID1 expression in primary breast tumours we used a previously published meta-analysis consisting of six groups of tumours on Affymetrix arrays totaling 1 107 samples." (PMID 21955753, 2011). "The amplification and co-amplification with other chromosomes of 11q13 region of chromosome 11 is relatively frequent in breast tumors and overexpression of CCND1 (cyclin D1) and PPP1CA is also seen." (PMID 17883861, 2007). "ZC3H12D degraded the mRNAs of CCND1 and other cell cycle‐promoting genes by binding to the conserved stem–loop structure localized in the 3′UTR via its RNase domain, thereby inhibiting their expression and the G1/S phase transition of breast tumor cells." (PMID 41263459, 2025). "Moreover, the protein expression of CCND1 and other cell cycle‐promoting genes was also increased by DDX5 in breast tumor cells." (PMID 41263459, 2025). "Overall, we discovered that the RNA helicase DDX5 could bind to the stem–loop structure in the 3′UTR of the CCND1 mRNA to increase its stability, allowing it to resist the ZC3H12D‐induced mRNA degradation in breast tumor cells." (PMID 41263459, 2025). "In contrast to normal human epithelial cells, HR‐positive breast tumors proliferate via autocrine mechanisms that involve PR‐induced expression of RANKL, Wnt4, and cyclin D1, as well as PR‐induced activation of protein kinases including CDK2, c‐Src, CK2, MAPK, and PI3K/AKT." (PMID 34714554, 2022). "Likewise, it has been shown that miR–92 can act as a tumour suppressor in breast tumours by inhibiting expression of AIB1 and/ or cyclin D1." (PMID 26437339, 2015). "Three-quarters of triple-negative BCs harbour at least one amplicon, however, their recurrence rates are lower than those of high-level CNAs found in ER-positive/ HER2-negative and HER2-positive BC subtypes (e.g. ERBB2-amplicon in HER2, and CCND1 and FGFR1 in luminal breast tumours)." (PMID 23151021, 2012). "From this study, we conclude that development of (pre-malignant) breast tumors in either wild type or MMTV-cyclin D1 mice was not augmented due to mammary gland targeted overexpression of human cortactin." (PMID 16536875, 2006). "From this study, we can conclude that development of (pre-malignant) breast tumors in either wild type or MMTV-cyclin D1 mice was not augmented due to mammary gland targeted overexpression of human cortactin." (PMID 16536875, 2006). "Moreover, the activity of Wnt/β-catenin signaling is enhanced only in a subset of breast tumor tissues, and the correlation between Wnt/β-catenin activity and c-Myc or cyclin D1 expression was not consistent among reports." (PMID 30857262, 2019). "Thus, we studied the effects of ICI-182,780 and E2 on CCND1 expression in calcitriol-treated ERα-negative breast tumor-derived cells." (PMID 24678876, 2014). "HR+ breast tumors regardless of HER2 status (HR+/HER2+ and HR+/HER2−) were more likely to harbor CNAs in CCND1, FGF3, FGF4, and FGF19, which colocalizes in chromosome 11q13.3." (PMID 32695676, 2020).
non-small cell lung carcinoma (103 papers, 1996 to 2025). A group of at least three distinct histological types of lung cancer, including non-small cell squamous cell carcinoma, adenocarcinoma, and large cell carcinoma. "For instance, in copy number omics, we discover pathways corresponding to genes like EGFR, CDK6, RASSF5, BRAF, and CCND1, which are associated with non-small cell lung cancer." (PMID 40191608, 2025). "Galectin-3 associated with cyclin D1 expression was also studied in non-small cell lung cancer." (PMID 30410421, 2018). "For instance, studies exploring the correlation between CCND1 and prognosis in non-small cell lung cancer (NSCLC) reported contrasting results, including positive correlation, inverse correlation, or negligible influence." (PMID 41404730, 2025). "miR-3940-5p suppresses the proliferation of non-small cell lung cancer cells by targeting cyclin D1 and ubiquitin specific peptidase-28." (PMID 38501059, 2024). "In a previous study, hsa-miR-326 was found to inhibit the development of non-small cell lung cancer by directly regulating the CCND1 gene." (PMID 39057123, 2024). "Activation of the Rac1-P38-ATF2 signaling pathway in non-small cell lung cancer cells has been documented to upregulate the expressions of Cyclin A2, Cyclin D1, and MMP2 proteins, thus promoting tumor growth." (PMID 39633985, 2024). "KLF4 also inhibits the tumor proliferation and metastasis of non-small cell lung cancer (NSCLC) through downregulating cyclin D1, upregulating p21, and inhibiting MSI2: an activator of the JAK/STAT3 signaling pathway that promotes metastasis." (PMID 37760529, 2023). "Lamin B2 promotes the malignant phenotype of non-small cell lung cancer cells by interacting with micro chromosome maintenance protein 7 and Cyclin D1, both of which increase tumor motility and tumor cell epithelial-mesenchymal transition." (PMID 35745729, 2022). "In the non-small-cell lung cancer cell line A549, stellettin B ablated the expression of cyclin D1 and phosphorylated Rb and upregulated p27 levels, leading to G1 phase arrest, an increase in cleaved PARP levels, ROS overproduction, and apoptosis." (PMID 35955957, 2022). "MIR503HG suppresses cell cycle arrest by decreasing cyclin D1 expression, thereby impeding the proliferation of non-small cell lung cancer cells." (PMID 35771155, 2022). "DF1, as an oncogene, has been reported to increase G0/G1 cells by regulating CDK2, CDK4, and cyclin D1 translational efficiency in non-small cell lung cancer (NSCLC)." (PMID 35351856, 2022). "Overexpression of miR-21 in non-small cell lung cancer up-regulated the expression of cyclin D1 and cyclin E1, respectively." (PMID 35154284, 2022). "Previous studies show that c-Jun regulates cell proliferation in non-small cell lung cancer by targeting CCND1." (PMID 34959221, 2021). "In a paper on non-small cell lung cancer Qin and Chen noted that low concentrations of CsA increased the phosphorylation of Akt, increased expression of Cyclin D1, and decreased expression of p27." (PMID 34858847, 2021). "Previous studies have shown that c-Jun regulates the proliferation of non-small cell lung cancer by targeting CCND1." (PMID 34368121, 2021). "Other functional experiments have demonstrated that piR-651 promotes tumor formation in non-small cell lung cancer mediated by Cyclin D1 and CDK4." (PMID 32357464, 2020). "Cyclin D1 overexpression is reported in 18–76% of evaluated patients and CCND1 gene amplification in 5–32% of non-small cell lung carcinoma patients (NSCLC)." (PMID 33317149, 2020). "miR-146a-5p acts as an oncosuppressor in non-small-cell lung cancer, inhibiting tumor cell proliferation by direct targeting of cyclin D1 and cyclin D2." (PMID 30611259, 2019). "For example, DDX5 promotes the proliferation of non-small-cell lung cancer cells for tumorigenesis by directly interacting with β-catenin to promote the transcription of cyclin D1 and c-Myc." (PMID 27835882, 2016).
non-small cell lung carcinoma (continued). "Cyclin D1 gene is amplified in non-small cell lung cancer (NSCLC) and cyclin D1 protein is frequently overexpressed in tumours and pre-invasive bronchial lesions." (PMID 25625291, 2015). "Non-small cell lung cancer cells transfected with cyclin D1-targeted siRNA exhibited a marked decrease in cell growth rate and invasive capacity." (PMID 25760437, 2015). "Other authors didn't confirm the prognostic value of cyclin D1 expression in resectable non small cell lung cancer." (PMID 22024187, 2011). "We didn't reveal any important correlations between clinicopathological findings and galectin-3 and cyclin D1 expression and in non small cell lung cancer." (PMID 22024187, 2011). "The aim of this study was the evaluation of correlations between clinicopathological findings and cyclin D1 and galectin-3 expression in non-small cell lung cancer." (PMID 22024187, 2011). "The aim of this study was the evaluation of correlations between clinicopathological findings and cyclin D1 and galectin-3 expression in non-small cell lung cancer (NSCLC)." (PMID 22024187, 2011). "We performed a retrospective study on the cyclin D1 expression in non-small cell lung cancer (NSCLC) according to the clinical characteristics." (PMID 20704822, 2010). "The correlation between cyclin D1 overexpression and the high histological grade was also reported in other tumor types including non-small cell lung carcinomas and squamous cell carcinomas of the larynx." (PMID 15385053, 2004). "Cyclin D1 gene amplification is an important event in many cancers, but it is rarely found in non-small-cell lung cancer (NSCLC)." (PMID 10574260, 1999). "Overexpression of BTG1 inhibited the proliferation, migration and invasion of hepatocytes, thyroid, nasopharynx, esophagus, breast and non-small cell lung cancer cells and induced apoptosis and cell cycle arrest by downregulating the expression of Cyclin D1, Bcl-2 and MMP-9." (PMID 36339000, 2022). "MiR-326 was reported to regulate cyclin D1 expression in non-small-cell lung cancer development." (PMID 32766125, 2020). "When Cul4b was knocked down in colorectal and non-small cell lung cancer cell lines, both cell proliferation and invasion were suppressed, concomitant with the inhibition of positive cell cycle regulators, including cyclin D1." (PMID 31260508, 2019). "In addition, another study in non-small cell lung cancer observed higher expression of cyclin D1 in galectin-3 free tumor tissues." (PMID 31832021, 2019). "CCND1 amplification has also been described in 12% of non-small cell lung cancers and in up to 41% of esophageal squamous cell carcinomas, suggesting that this could be one of the more common genetic alterations linked to smoking-induced epithelial malignancy." (PMID 23718828, 2013). "Lung tumours and their corresponding tumour-free resection margins from 33 patients who underwent resection of non-small-cell lung cancer (NSCLC) were examined by immunostaining with monoclonal antibodies against cyclin D1 (DCS-6; Novocastra) and pRb (NCL Rb-1; Novocastra)." (PMID 9192978, 1997). "In addition to its normal function, the high expression of FXR was found to positively regulate the cancer cell proliferation and tumour growth, which might involve the activation of several oncogenes like cyclin D1 in non-small cell lung cancer (NSCLC)." (PMID 35006466, 2021). "Indeed, an upregulation of TRPC1 protein level in the G1 compared with G0 was observed in Ehrlich Lettré Ascites (ELA) cells while TRPC1silencing in non-small cell lung carcinoma cell lines decreased cyclin D1 and D3 expression levels, resulting in G0/G1 cell cycle arrest." (PMID 27183905, 2016). "Multiple studies have shown that miRNAs like miR-205 promote tumor progression in non-small cell lung cancer (NSCLC) by downregulating SMAD4 to inhibit p21 expression, while miR-146a-5p and miR-15a suppress cell cycle progression by targeting Cyclin D1/D2." (PMID 41002349, 2025).